SRC (SRC proto-oncogene, non-receptor tyrosine kinase)
Diseases named in the same sentence as SRC in open-access papers (continued):
Sharing a sentence is not in itself a finding about the gene and the disease.
chondrosarcoma (18 papers, 2010 to 2024). A malignant cartilaginous matrix-producing mesenchymal neoplasm arising from the bone and soft tissue. "In the 8 doxorubicin resistant chondrosarcoma cell lines utilized in this study, SRC inhibition was found to overcome doxorubicin resistance by inducing apoptosis and inhibiting migration." (PMID 34938658, 2021). "This review focuses on metabolic changes in chondrosarcoma, and the relationship between signaling via isocitrate dehydrogenase 1 and 2 (IDH1 and IDH2), hedgehog, PI3K-mTOR-AKT, and SRC, as well as histone acetylation and angiogenesis." (PMID 34938658, 2021). "In chondrosarcoma, negative regulators of the intrinsic or mitochondrial apoptotic pathway such as BCL2, which has crosstalk with SRC, are upregulated and mediate chemo-resistance in cancer." (PMID 34938658, 2021). "The multifunctional tyrosine kinase inhibitor Dasatinib (BMS-354825), which inhibits SRC and down-regulates BCL2 was studied in chondrosarcoma cell lines." (PMID 34938658, 2021). "Targeting IDH mutations, lipid, glucose and mitochondrial metabolic targets, hedgehog, PI3K/Akt/MTOR, HIF and SRC pathways have yielded mixed results in clinical studies without clear therapeutic options in chondrosarcoma." (PMID 34938658, 2021). "Here, we found that both the SRC inhibitor dasatinib or the FAK inhibitor PF-573228 were able to dose-dependently inhibit cell invasion, thus indicating that this mechanism is also mediating invasion in chondrosarcoma cell lines." (PMID 30987403, 2019). "In addition, inhibition of the YAP/TAZ-activating kinases SRC and RAC was reported to interfere with the migratory and invasive properties of chondrosarcoma cells, while BMP-7-induced SRC activation promoted chondrosarcoma cell migration." (PMID 32326412, 2020).
chronic myeloid leukemia (18 papers, 2014 to 2026). "We next used evaluated bosutinib, a dual SRC/ABL kinase inhibitor that is FDA approved for chronic myelogenous leukemia treatment." (PMID 36752207, 2023). "Dasatinib, along with other TKIs, is an ABL/SRC tyrosine kinase inhibitor used in the first-line treatment of chronic myeloid leukaemia (CML) and potently induces apoptosis of CML cells." (PMID 36560403, 2022). "Results showed that DMP11 at a dose of 5 nM significantly degraded the BCR-ABL fusion protein of wild-type and imatinib-resistant chronic myeloid leukemia cell lines and found that the SRC protein (Yes/Fyn/Fgr) also showed a dose-dependent degradative effect." (PMID 36349200, 2022). "For instance, dasatinib was approved to treat chronic myeloid leukemia, whereas SRC-based therapy for HNSCC is limited." (PMID 35873484, 2022). "For example, bosutinib, dasatinib, and ponatinib are SRC/multikinase inhibitors that are approved by the FDA for the treatment of chronic myelogenous leukemia." (PMID 34764976, 2021). "Indeed, the SRC inhibitors dasatinib and bosutinib have been approved for clinical usage in the treatment of chronic myeloid leukemia, and KX2-391 has been approved for the treatment of actinic keratosis and for the prevention of the development of actinic keratosis into squamous cell carcinoma." (PMID 37046850, 2023). "Dasatinib (D) inhibits several kinases including SRC and ABL and is currently used as a second line chemotherapeutic agent against imatinib‐resistant chronic myeloid leukemia." (PMID 41462563, 2026). "In this study, we applied two SFK-targeted inhibitors: dasatinib, approved by the FDA for chronic myeloid leukemia 36, and NXP900, a novel SRC/YES1-inhibitor currently undergoing clinical trial (NCT05873686)." (PMID 39776795, 2025). "When wild-type and drug-resistant chronic myeloid leukemia cells were incubated with DMP11 for 24 hours, the fusion protein became significantly degraded, and the SRC protein (Yes/Fyn/Fgr) was also degraded." (PMID 36349200, 2022). "These four compounds were developed as inhibitors to BCR-ABL for the treatment of chronic myeloid leukaemia, but have since been found to have a number of novel kinase and non-kinase targets, including SRC and DDR2." (PMID 35406381, 2022). "To study if the selectivity profile of eCF506 translate into weaker phenotypic activity against ABL-driven cancer cells relative to classical SRC/ABL inhibitors, we performed cell proliferation assays with three BCR-ABL-positive chronic myeloid leukemia (CML) cell lines: LAMA-84, KCL-22, and K-562." (PMID 34417202, 2021).
lung adenocarcinoma (18 papers, 2014 to 2026). A carcinoma that arises from the lung and is characterized by the presence of malignant glandular epithelial cells. "Our study provides a new model for the negative regulation of uPA by KLF17 in mediating the invasion of lung adenocarcinoma via the SRC/P38/MAPK pathway." (PMID 28454121, 2017). "The correlation between miR-203 and SRC was further examined by evaluating SRC expression in human lung adenocarcinoma A549 cells after overexpression of miR-203." (PMID 25140799, 2014). "We detected SRC expression in the human lung squamous cell carcinoma (LUSC) and human lung adenocarcinoma (LUAD) transcriptome datasets from The Cancer Genome Atlas (TCGA) to determine whether our findings have clinical implications." (PMID 40599804, 2025). "Furthermore, we found that the SRC protein level was higher in human lung adenocarcinoma A549 cells compared to that in normal lung fibroblast HLF cells, but the SRC mRNA level was equal in these two cell lines." (PMID 25140799, 2014).
sarcoma (17 papers, 2012 to 2025). A usually aggressive malignant neoplasm of the soft tissue or bone. "Protooncogene SRC, Rous sarcoma (SRC) associated in mitosis of 68 kD (Sam68) belongs to the STAR (Signal Transduction and Activation of RNA metabolism) family of RBPs, which regulate several aspects of RNA metabolism." (PMID 32753528, 2020). "Gene expression profiling of leiomyosarcomas and undifferentiated pleomorphic sarcomas has suggested that SRC can be employed as a diagnostic marker." (PMID 26788073, 2016). "BK40196 is a dual c-KIT/c-Abl (Abelson) inhibitor but also displays binding affinity to other kinases, including fused in sarcoma (SRC) and FYN." (PMID 40137158, 2025). "In vitro experiments using sarcoma (SRC) agonists and inhibitors were performed to investigate the impact of ACNO therapy on the expression of SRC, STAT3, and other proteins in HaCaT cells." (PMID 40066291, 2025). "The SRC signaling cascade, crucial in sarcoma survival, migration, and proliferation, regulates PI3K–AKT signaling." (PMID 39590345, 2024). "Exposure of sarcoma cells to [pazopanib + entinostat] caused activation of ERBB1 and c-SRC and in a cell-specific fashion, activations of ERBB2, c-KIT, and c-MET." (PMID 31380285, 2019). "Exposure of sarcoma cells to [pazopanib + entinostat] caused activation of ERBB1, ERBB2, c-KIT, c-MET, and c-SRC." (PMID 31380285, 2019). "SRC was the most value discriminator to distinguish both sarcomas and presented the highest number of interaction in the in silico protein-protein analysis." (PMID 25028927, 2014). "Analysis using the U133Plus gene expressions expands this result by including JUN (JUN oncogene), MAPK8 (mitogen activated protein kinase 8), SRC (v-SRC sarcoma) and FYN (FYN oncogene related to SRC) as protein kinases within dasatinib’s discriminating genes." (PMID 23056181, 2012). "SRC, encoded by the sarcoma gene, is a non-receptor tyrosine kinase and the proto-oncogene c-Src product involved in cell survival, angiogenesis, proliferation, and motility." (PMID 38892472, 2024). "This, in turn, activates the SRC–rat sarcoma–extracellular signal-regulated kinase (SRC-RAS-ERK) and phosphoinositide 3-kinase/protein kinase B (PI3K/AKT), and mitogen-activated protein kinase (MAPK) downstream signaling pathways, which are responsible for cell proliferation." (PMID 38104126, 2023). "Deregulated SRC/FAK (Steroid receptor coactivator/Focal adhesion kinase) signaling is related to enhanced migration and invasion in many types of tumors and we previously found that several sarcoma models may invade through a mechanism depending on SRC/FAK signaling." (PMID 30987403, 2019). "Dasatinib, a potent inhibitor of SRC (SaRComa) family kinases, is currently under development against a variety of tumor types." (PMID 23056181, 2012). "Targeting the downstream pathway of SRC is only one of various possible mechanisms and is not expected therefore to be a universal mechanism to sensitize sarcomas to doxorubicin." (PMID 26788073, 2016). "However, despite the potential of SRC pathway inhibition, a phase II trial of dasatinib in high-grade sarcoma patients showed no clinical benefit." (PMID 39590345, 2024). "Finally, as a standard of care drug in sarcoma and renal carcinoma pazopanib is dosed daily and would thus be likely to block any compensatory survival signaling through PDGFRα/PDGFRβ/FGFR, but not through c-MET or SRC-linked cytokine receptors." (PMID 28146421, 2017).
cervical carcinoma (16 papers, 2009 to 2025). A carcinoma arising from either the exocervical squamous epithelium or the endocervical glandular epithelium. "The results suggest that LIMK1 promotes the invasion, metastasis, and proliferation of cervical cancer cells and promotes cervical cancer development by regulating the oxidative stress/SRC-mediated p-FAK/p-ROCK1/2/p-Cofilin-1 pathway." (PMID 38975937, 2024). "Immunofluorescence imaging indicated that CT45A1 changed the SRC protein localization from the sub-cellular membrane to the cytoplasm and nucleus in cervical cancer cells." (PMID 37924456, 2024). "CT45A1 promotes cervical cancer cell tumorigenesis, neovascularization, and drug resistance by activating oncogenic SRC and downstream tumorigenic signaling pathways." (PMID 37924456, 2024). "Phosphorylated AKT and phosphorylated SRC both have higher levels of expression in cervical cancer, including higher levels in invasive samples than in precancers." (PMID 37509353, 2023). "Overexpressed NEDD9 promotes cell migration and invasion in cervical cancer cells, probably via regulating tyrosine dephosphorylation of FAK and SRC and the expression of EMT-associated protein E-cadherin." (PMID 24058594, 2013). "Silencing NEDD9 resulted in tyrosine dephosphorylation of FAK and SRC oncoproteins, and decreased cell migration and invasion in the cervical carcinoma SiHa and HeLa cells." (PMID 24058594, 2013). "Additionally, co-immunoprecipitation (Co-IP) revealed that CT45A1 was able to directly bind to the SRC protein in cervical cancer cells." (PMID 37924456, 2024). "In addition, we also found that LIMK1 can contribute to the development of cervical cancer by regulating oxidative stress and SRC-mediated signaling pathways." (PMID 38975937, 2024). "Indeed, HPV-16 E7 leads to the expression of p-AKT and p-SRC, which then stimulates the initiation and progression of cervical cancer." (PMID 37509353, 2023). "Overexpression and/or activation of tumorigenic signaling proteins, including FN1, SRC, CREB, YAP, and TAZ, play a critical role in the progression of cervical cancer." (PMID 37924456, 2024). "Convincingly, the SRC-specific inhibitor 6-dimethylamino-2-phenyl-3(2H)-pyridazinone (PP2) markedly suppressed CT45A1-mediated SRC-ERK-CREB activation and inhibited cervical cancer cell migration." (PMID 37924456, 2024). "Oleic acid induces CD36 via SRC/ERK activation, which contributes to cervical cancer formation and the progression of cervical cancer." (PMID 34959830, 2021). "Additionally, lycorine inhibited the phosphorylation of oncogenic SRC and ERK in a concentration-dependent manner, reduced cervical cancer cell colony numbers, and decreased HeLa cell invasion." (PMID 37924456, 2024). "Our findings suggest that NEDD9 is overexpressed in cervical cancer tissues and cells, and overexpressed NEDD9 promotes migration and invasion in cervical carcinoma cells, probably via a positive feedback loop of tyrosine phosphorylation between NEDD9 and FAK or SRC." (PMID 24058594, 2013).
leukemia (16 papers, 2014 to 2026). A malignant (clonal) hematologic disorder, involving hematopoietic stem cells and characterized by the presence of primitive or atypical myeloid or lymphoid cells in the bone marrow and the blood. "For early naïve culture we used 5iLA conditions (MEK inhibitor, GSK3 inhibitor, ROCK inhibitor, BRAF inhibitor and SRC inhibitor with human leukemia inhibitor factor (hLIF) and Activin A;)." (PMID 37702917, 2023). "This proapoptotic process is thought to be driven by both oncogene and tumour suppressor gene and has been suggested as a putative mechanism of SRC in leukemia." (PMID 25587468, 2014). "High SRC expression was linked to adverse ELN/FAB features, increased immune checkpoint expression, enrichment of inflammatory and immunoregulatory pathways, and a higher proportion of primitive leukemia-associated cell states." (PMID 42123320, 2026). "In addition, we observed downregulation of leukemia-associated proto-oncogenes such as CCND1/2 (0.46, p < 0.05), CCNE2 (0.38 p = 0.0076), MYC (0.42, p < 0.001), SRC (0.3, p < 10−5), or MPL (0.25, p < 0.05)." (PMID 41438051, 2025). "In this study, we evaluated whether ponatinib, a BCR-ABL/SRC inhibitor approved for use in leukemia, could potentially be repurposed for treatment of NF2 schwannomas." (PMID 28427224, 2017). "Dasatinib, a potent SRC and SFK tyrosine kinase inhibitor, is approved for treating certain leukemia types, primarily due to its effectiveness against BCR-ABL fusion proteins that drive these malignancies." (PMID 40598793, 2025). "Regarding signaling through a family of different Src kinases (including LYN and SRC), these are expressed in AML and their phosphorylation regulates leukemia cell proliferation and survival (including through LYN mediating mTOR activation)." (PMID 35053339, 2022). "Surprisingly, despite the vast amount of evidence gathered over the years and the approval of dual SRC/ABL kinase inhibitors to treat BCR-ABL-positive leukemias, to date no kinase inhibitor has yet been approved for the treatment of SRC-active solid malignancies." (PMID 34417202, 2021). "Unfortunately, we were not able to study other cytoplasmic effectors such as ERK, SRC or STAT proteins that could be deregulated in leukemia." (PMID 29464086, 2018).
non-small cell lung carcinoma (16 papers, 2015 to 2026). A group of at least three distinct histological types of lung cancer, including non-small cell squamous cell carcinoma, adenocarcinoma, and large cell carcinoma. "Oncoproteins, including EGFR, GRB2, and SRC, have been reported to be enriched in the non-small cell lung cancer (NSCLC) exosomes, which promote the cancer’s development." (PMID 40006514, 2025). "Studies have also found that combined treatment using targeted MEK and SRC inhibitors synergistically abrogates tumor cell growth and induces mesenchymal–epithelial transition in non-small-cell lung carcinoma." (PMID 31428570, 2019). "Combining PD0325901 and SRC inhibitors suppressed tumor growth and induced mesenchymal to epithelial transition in non-small cell lung cancer cells." (PMID 29100331, 2017). "The protein kinases RAF and SRC are validated therapeutic targets in KRAS-mutant pancreatic ductal adenocarcinomas, colorectal, and non-small-cell lung cancers." (PMID 36547158, 2022). "Finally, EGFR inhibitors, Gefitinib and Erlotinib, and Src inhibitor, Dasatinib, are all shown to reduce the levels of SOX2 by blocking the EGFR/SRC/AKT signaling, eventually suppressing the self-renewal properties of cancer stem cells in non-small cell lung cancer." (PMID 31748974, 2020).
neuroblastoma (14 papers, 2013 to 2025). Neuroblastoma (NB) is the most common solid, extracranial childhood tumor. "Based on our data as well as previous reports, we conclude that the antitumoral activity of fosaprepitant is, indeed, due to selective TACR1 inhibition, and that TACR1 expression as well as SRC phosphorylation in primary neuroblastoma samples may be predictive for fosaprepitant sensitivity." (PMID 27888795, 2017). "Alternatively, for example in the context of neuroblastoma cell motility, FAK is required for integrin α5β1-mediated SRC phosphorylation." (PMID 28806779, 2017). "Similar to previous reports in other tumor entities, we detected decreased SRC phosphorylation following TACR1 inhibition, indicating that in neuroblastoma TACR1 might at least in part signal through SRC." (PMID 27888795, 2017). "As demonstrated with SRC, by looking at the specific differential connections of these genes we may find a biological mechanism, novel to neuroblastoma, that explains the difference between the HR and non-HR patients." (PMID 30940863, 2019).